IL1B (interleukin 1 beta)
Diseases named in the same sentence as IL1B in open-access papers (continued):
Sharing a sentence is not in itself a finding about the gene and the disease.
tumor (continued). "CXCL10 expression and its pathway components, NLRP3, NF-κB, and IL-1β, were markedly suppressed in tumor tissues from the calycosin-treated mice." (PMID 38461458, 2024). "Studies have illuminated the significant functions of key interleukins, including IL-6, IL-8, IL-1β, and IL-11, in promoting tumor growth, osteoclast development, and metastasis colonization in the skeletal system." (PMID 39125732, 2024). "In conclusion, our study demonstrates that ESP can effectively reduce IL-1β and IL-6 levels, suppress inflammation in RA, inhibit tumor-like proliferation of synovial cells, counteract NF-κB phosphorylation, and protect against joint damage in the RA model." (PMID 38846095, 2024). "Macrophages internalize p-MET, leading to increased levels of IL-1β and IL-6 mRNA and elevated IL-1α secretion, which fosters tumor growth." (PMID 39726601, 2024). "This process acts as a vicious cycle, in which M2-type TAM cells are stimulated by the tumor itself, releasing factors like TNF and interleukins such as IL-6, IL-1b, and IL-10, which promote tumor proliferation and survival." (PMID 38248305, 2024). "In alignment with our preclinical findings, cell-population profiling of human CRC samples identified tumor-infiltrating monocytes as the primary source of IL-1β production." (PMID 39030280, 2024). "Activated macrophages exerted anti-tumor effects by producing inflammatory cytokines like IL-1β, while the interaction between ITGB3 and MFGE8 inhibited macrophage IL-1β production by inducing necrotic cells and an ATP-dependent manner." (PMID 38183097, 2024). "IL-10 has been associated with inhibiting neovascularization and tumor metastasis by downregulating the synthesis of VEGF, IL-1β, TNF-α, IL-6, and MMP-9 in tumor-associated macrophages and natural killer (NK) cell-dependent mechanisms, respectively." (PMID 38672182, 2024). "TAM secretes vascular endothelial growth factor (VEGF), TGF-β, and IL-10, and low levels of TNF-α, IL-12, and IL-1β to induce tumor blood vessel growth and angiogenesis." (PMID 39000385, 2024). "This binding causes lymphocytes to release cytokines IL-2, IL-1b, IL-6, TNF and Ifny into the medium, which leads to the appearance of cytotoxic lymphocytes in PBMC capable of lysing HLA-negative tumor cells." (PMID 38203798, 2024). "Interventions that block signaling by IL-1β and IL-6 suppress tumor growth in various mouse models of PDAC." (PMID 39260693, 2024). "SLC7A11, a member of the amino acid transporter SLC7 family, is induced by IL‐1β to upregulate PD‐L1 and CSF1 through αKG/HIF1α axis, leading to infiltration of tumor‐associated macrophages and myeloid‐derived suppressor cells and promoting metastasis of HCC." (PMID 39041652, 2024). "The rupture of tumor cells undergoing pyroptosis releases a number of inflammatory factors, including IL-18, IL-1β, HSP, ATP, and HMGB1." (PMID 39575419, 2024). "In terms of the antitumor mechanism of CD39 antibodies, it has been indicated that CD39 blockade on macrophages and monocytes led to the activation of the NALP3 inflammasome and the release of IL-18 and IL-1β to exert anti-tumor effects." (PMID 39431011, 2024). "In a carcinogen-induced OSCC model, the intracellular ROS induced by 5-FU enhanced the NLRP3 inflammasome and IL-1β expression, which in turn mediated the onset of chemoresistance and tumor cell proliferation." (PMID 38904007, 2024). "Instead, we demonstrate the therapeutic potential of a transient deconstruction of inflammasomes in tumor cells with either IL-1β or IL-18 in combination with pyroptosis." (PMID 39737979, 2024). "In murine systems, the requirement of IFNγ for tumor Nos2 expression has been shown, which was amplified by other cytokines including IL1β and TNFα." (PMID 39356141, 2024). "By studying the interrelationship between tumor cells and immune cells, we found that OS cells affect IL1β+ macrophages through the TNF signaling pathway." (PMID 39767767, 2024).
tumor (continued). "IL-1B has been shown to facilitate tumour angiogenesis to promote tumour growth and distant metastasis." (PMID 38800348, 2024). "Our findings indicate that both MLT group and si-NLRP3 group significantly suppressed the mRNA and protein expression levels of NLRP3 and downstream IL-1β in tumor tissues." (PMID 39230586, 2024). "In vitro experiments showed that knockdown of IL-1β significantly inhibited cell proliferation, migration, and invasion, while overexpression of IL-1β exhibited the opposite effect, indicating the role of IL-1β as a tumor promoter in ESCC." (PMID 38762529, 2024). "Anakinra, an inflammasome recombinant IL1 receptor antagonist, blocks both IL1α and IL1β, showing potential in reducing tumor-related inflammation." (PMID 39766086, 2024). "Polyphenols like curcumin (from turmeric) and quercetin (from fruits and vegetables) reduce the secretion of cytokines driving inflammation, such as TNF-α, IL-6, and IL-1β, related to prolonged inflammation response and tumor progression." (PMID 39683540, 2024). "IL-1β is also a major effector molecule in the inflammasome pathway, regulating and activating inflammatory responses as well as encouraging tumor cell proliferation." (PMID 38780447, 2024). "Neutrophils played a role in facilitating the extravasation of tumor cells in lung parenchyma through the secretion of IL-1β and matrix metalloproteinases." (PMID 38474175, 2024). "We show that BCG induced the recruitment and polarization of macrophages towards a pro-inflammatory phenotype, accompanied by induction of the inflammatory cytokines tnfa, il1b and il6 in the tumor microenvironment." (PMID 39114912, 2024). "M1 are pro-inflammatory macrophages that act as tumor suppressors by releasing large amounts of pro-inflammatory cytokines (e.g., IL-1β, TNF-α, and IFN-β) accompanied by driving the immune response of powerful T cells and cytotoxic cells." (PMID 38553639, 2024). "A weak but significant correlation was observed between TIB density and tumor IL-1β expression in invasive TNBC (Spearman’s rho = 0.168, p = 0.024)." (PMID 39801513, 2024). "Inflammatory cytokines such as IL6 (and IL8, IL1B) are implicated in GBM tumorigenicity and progression, and IL6 in particular leads to JAK-STAT pro-tumor signaling." (PMID 39585062, 2024). "Activated caspase-1 promotes proteolytic cleavage of pro-IL-1β, allowing IL-1β maturation, and tumor-associated macrophages recruitment to the TME and, therefore, tumor progression." (PMID 39625520, 2024). "Consistent with cytokine profiling, real-time PCR data confirmed upregulation in the expression of IL8, Cxcl10, Il1β, and Ccl2 in tumor lysates." (PMID 39768223, 2024). "The HFD increased immune suppressive MDSC in the blood, limiting the activation of tumor-reactive CD8+ T cells, and the HFD-induced tumor microenvironment showed elevated levels of IL-1β and IFNγ mRNA levels in 4T1 cell-bearing mice." (PMID 38999849, 2024). "It has been shown that in the TME, dying tumor cells release the inflammatory precursor IL-1α, which, similar to IL-1β, increases tumor invasiveness and angiogenesis." (PMID 38553639, 2024). "According to reports, during the pathogenesis of COAD, M2-like macrophages secrete IL-1β, which induces Wnt signaling and supports tumor cell growth." (PMID 39408824, 2024). "The proinflammatory cytokines IL-15, IL-18, and IL-1β profiles reveal a significant host serum increase after day 35 when the tumor began to progress in growth." (PMID 39451257, 2024). "Considering the tumor-promoting nature of IL-1β, lower IL-1β levels induced by the combination therapy of RT + ATMi are preferable." (PMID 39411143, 2024). "To ensure that the IL-1β detected was secreted solely by the tumor cells, we cultured the cell lines with B cells for 24 hours, after which the B cells were removed." (PMID 39801513, 2024).
tumor (continued). "Since it is known that IL‐1β and IL‐18 antagonism of tumour immune responses needs to be discussed depending on the type of cancer, it will not be discussed in detail here and has been summarized in an excellent review." (PMID 38652105, 2024). "The expression of IL-1, particularly IL-1β, in bone metastases significantly influences the activation and regulation of immune cells, contributing to the complex interplay within the tumor microenvironment." (PMID 39125732, 2024). "IL‐1RA and IL‐1β were detected in shed tumor cells from the treated patients, as well as IFN‐α2 and IL‐17D." (PMID 38553868, 2024). "The increase in IL-1β allows the establishment of an inflammatory tumor microenvironment (TME) and induces EMT and EMT memory through activation of the EMT transcription factors Snail and Slug." (PMID 38254674, 2024). "Ligands of IL1 receptor inhibitor with receptors of IL1RN and IL1B shared similar roles in immune escape and tumor metastasis." (PMID 38944814, 2024). "DCs release IL-1β in response to tumor antigens and bacterial components, activating CD8+ T cell lymphocytes." (PMID 39594765, 2024). "Our results showed a favorable association between tumor-infiltrating immune cells and FN1, CXCL8, IL1β, and ITIH4." (PMID 38637796, 2024). "IL-1β, another pro-inflammatory cytokine, involved in tumor growth and metastasis, activates NF-κB, upregulates COX-2 and leads to chemoresistance in pancreatic adenocarcinoma." (PMID 39195299, 2024). "Here the authors report a toolbox of gasdermin D variants for induction of pyroptosis, showing that, when combined with intratumoral expression of cytokines (IL-1β, IL-12, or IL-18), anti-tumor immune responses in preclinical models are enhanced." (PMID 39737979, 2024). "In gastric cancer, a high level of TG2 activity enhanced inflammation and tumor growth by recruiting macrophages to the tumor via the IL-1β-mediated induction of CCL2 and CXCL10." (PMID 38474044, 2024). "Tumor-derived factors (i.e., IL-6, IL-10, IL-1β, PGE2, VEGF, GM-CSF, M-CSF, and IFN-γ) have been reported to induce MDSCs." (PMID 39272914, 2024). "Taken together, it appears that activation of proinflammatory cytokines all have the potential to promote carcinogenesis, but IL-1B seems to be the dominant cytokine that drives these pro-tumour processes." (PMID 38800348, 2024). "BRDs and BETs can inhibit or activate the assembly of the transcriptional machinery regulating the production of inflammatory cytokines with crucial functions in tumor progression (IL-1b, IL-6, TNFa, and MCP-1)." (PMID 39516356, 2024). "In a lung tumor model, researchers identified the impact of neutrophil NOX2-derived ROS in facilitating tumor colonization through an IL-1β-dependent pathway." (PMID 38474175, 2024). "Conversely, while IL-1β has been shown to possess anti-tumor cell proliferative effects, its impact on ATC remains undefined." (PMID 38403820, 2024). "It has been found that large amounts of IL-1β are present in tumors, which are mainly produced by immune or malignant cells in the tumor microenvironment (TME) and severely influence the course of malignant tumors." (PMID 38762529, 2024). "IL-1β produced during chronic inflammatory processes has been reported to support tumor development." (PMID 38762529, 2024). "Typically, M1 macrophages are induced by LPS and IFN-γ, and they produce pro-inflammatory cytokines, including IL-6, TNF-α, and IL-1β, which possess potent anti-tumor effects." (PMID 39795180, 2024). "BMSCs contribute to the pro-inflammatory tumor microenvironment by expressing key factors such as IL-1β, TNFα, LIF, and COX2, which support MM proliferation." (PMID 39609411, 2024). "Taken together, the low levels of IL‐12p70, IL‐23, and IFN‐β combined with high level of IL‐1β are likely to contribute to the tumor mass increase observed." (PMID 38600057, 2024).
tumor (continued). "Measurement of tumor volume throughout the culture of the animal model manifested that tumor growth was significantly accelerated in the overexpression of the IL-1β group compared with the vector group (P < 0.05)." (PMID 38762529, 2024). "NLRP3 is a multiprotein complex that regulates macrophages, promoting secretion of pro-inflammatory cytokines such IL-18 and IL-1β by macrophages and this in turn was shown to optimize anti-tumor activity of NK cells and restrict tumor growth." (PMID 38533720, 2024). "As well as macrophages, IL-1β production by dendritic cells within the tumour microenvironment was also shown to be induced by intravenous S. typhimurium treatment in a subcutaneous colorectal cancer model." (PMID 39272829, 2024). "For example, the pro-inflammatory factors TNF-α, IL-6, and IL-1β promote tumor growth, invasion, and metastasis." (PMID 38368407, 2024). "In the skeletal muscle, IL‐1β mRNA expression was elevated in the tumor group by 79.55% (p = 0.012), and by 116.90% (p = 0.002) in the heart." (PMID 39294861, 2024). "Due to the prevailing thought that IL-1β promotes tumor progression, many clinical trials aim to block IL-1β signaling as an anticancer therapy." (PMID 38391959, 2024). "In turn, the SH animals were characterized by high expression of Tnfa in tumor tissue and Il1b both in the tumors and in the peritumoral area compared with the control group." (PMID 39063041, 2024). "PDGF platelet-derived growth is the most potent mitogenic signal, along with integrins, pro-inflammatory JNK activation by the cytokine IL-1β can alter TGF-β signaling from tumor suppression to oncogenesis." (PMID 39608222, 2024). "Knocking out Dectin-1 resulted in reduced IL-1β levels and decreased proportions of Tregs and MDSCs in oral squamous cell carcinoma in mice, leading to slower tumor progression and reduced tumor burden." (PMID 39590166, 2024). "Blocking IL-1β also helped to reduce tumor progression, but combining IL-1α/IL-1β blockade or targeting them both using the IL-1R1 antagonist anakinra most effectively disrupted tumor initiation." (PMID 39236155, 2024). "Notch1 promotes the production of proinflammatory cytokines such as CCL2 and IL-1β, which improves the recruitment of tumor-promoting TAMs to the TME." (PMID 39735530, 2024). "Anti-TNF-α and anti-IL-1β in SPP1-OE supernatant had similar effect on tumor cells compared with VGX-1027." (PMID 39726047, 2024). "In primary tumors, IL-1β inhibits growth by reducing the infiltration of anti-tumor immune cells but promotes cell migration." (PMID 39125732, 2024). "Further analysis of the differential expression of IL-1 family and related genes in normal tissues and HPV- and HPV+ tumor tissues revealed that IL-1α, IL-1β, IL1R1, IL1R2, IL1RL1, IL1RAP, IL1F10, IL-18 and CASP1 were highly expressed in HPV- tumors." (PMID 39461030, 2024). "Transcriptional analyses of metformin-treated mouse bone marrow-derived macrophages show decreased expression levels of pro-tumour genes, including Tgfbi and Il1β, related to enhanced mTOR/HIF1α signalling and metabolic rewiring towards glycolysis." (PMID 39315158, 2024). "In tumor biology, interleukins as IL-1b, IL-8, IL-6 promote cell proliferation and epithelial-mesenchymal transition (EMT), but IL-6 also influences cell cycle arrest and immune clearance of damaged cells, as well as CCL2 and CXCL1." (PMID 38175424, 2024). "Specifically, after pyroptosis, the cells promote the release of cytokines such as IL‐1β and IL‐18, which can have an effect on tumour development and metastasis." (PMID 38652105, 2024). "NF-κB plays an important role in CAFs, mediating the upregulation of proteases such as COX2, CXCL1, CXCL2, CYR61/CCN1, IL-1β, IL-6, and osteopontin, thus promote tumor growth, recruit macrophages, and form tumor vasculature." (PMID 39146202, 2024).
tumor (continued). "Tumor microenvironment-derived IL-1β is an important mediator for angiogenesis and inhibition of IL-1 and IL-1 receptor antagonists reduced angiogenic response and tumor growth." (PMID 39559365, 2024). "High IL-1β expression was defined as staining intensity per area in tumor cells above the median score, observed in 26% (33 out of 90) of samples." (PMID 39801513, 2024). "Prostaglandin E2 (PGE2) and TNF were the TME factors able to elicit the IL-1β+ TAM population with an inflammatory loop between tumor cells and IL-1β-expressing TAM, sustaining tumor growth." (PMID 38334625, 2024). "It has been demonstrated that IL1β, despite its pro-inflammatory activity, is also involved in tumour progression and immune escape mechanisms." (PMID 39315158, 2024). "Tumor-derived IL1β activates γδ T to produce high levels of IL-17, which leads to neutrophil expansion and altered neutrophil phenotype." (PMID 36835413, 2023). "Interleukin (IL)‐1β, in turn, drove an immune inhibitory phenotype on tumor cells, especially on the increase in programmed death‐ligand 1, by activating the nuclear factor‐κB (NF‐κB) signaling pathway." (PMID 37009412, 2023). "The reduction of NLRP3 in the S1PR1-KO CD11bhi TAMs group as compared with the WT group decreased IL-1β levels in tumor extracellular fluid more significantly." (PMID 37542283, 2023). "IL-1β is known to enhance proinflammatory and anti-tumor effects and help the recruitment of immune cells, and IL-6 can be produced by various immune cells and shows both proinflammatory and anti-inflammatory roles according to the surrounding environment." (PMID 37242761, 2023). "DNA damage enhanced IL-1β expression and ROS production; IL-1β blocks mutant cell elimination and neighboring cell proliferation, and ROS senesces neighboring cells, resulting in heterogeneous tumor formation." (PMID 37164759, 2023). "An increase in tumor metabolite lactate was concomitant with increase in proinflammatory cytokine IL-1b and circadian factors Clock and Bmal1." (PMID 37476290, 2023). "Increased expression of IL-1α and IL-1β has been reported in numerous cancers, where their tumor-promoting roles have been established." (PMID 37733448, 2023). "Together, this study presents an IL‐1β‐centered immunosuppressive loop between TAMs and tumor cells, highlighting IL‐1β as a candidate therapeutic target to reverse immunosuppression and potentiate immune checkpoint blockade." (PMID 37009412, 2023). "While often critical for the immune response to pathogens, pro-inflammatory cytokines (TNFα, IL-1β, and IL-6) play mixed roles in tumor pathogenesis." (PMID 37461742, 2023). "To evaluate the effect of IL‐1β in tumor growth, we further used the IL‐1β antibody and MCC950 for in vivo studies." (PMID 38116060, 2023). "In summary, our findings indicated that elevated levels of NLRP3/IL‐1β in tumor cells contribute to oxaliplatin resistance and tumor progression through the modulation of PMN‐MDSC recruitment and PD‐L1 expression." (PMID 38116060, 2023). "These genes included those related to P/DAMP signaling (e.g., Il6, Tlr1, Tlr4, Il1b, Il18), necroptotic tumor cell death (e.g., Casp1, Casp8, Il1b), and activation of the adaptive immune system (e.g., Cd80, Cd8a, Ccr5, Cxcl10)." (PMID 37213298, 2023). "IL-1β is a pro-inflammatory cytokine in BC that is secreted by monocytes, dendritic cells (DCs), macrophages, CAAs, and tumor cells." (PMID 36765683, 2023). "Although IL-1α and IL-1β both signal through the same ubiquitously expressed receptor (IL-1R1) on all cells, the resulting effects on tumor biology can be distinct and tissue specific." (PMID 37733448, 2023). "To evaluate the therapeutic potential of blocking the IL‐1β pathway in preventing the settlement of circulating tumor cells in the lungs after surgery, we established a surgical trauma model in IL‐1β genetic knocked‐out mice (IL‐1β−/−)." (PMID 37585564, 2023).